MIR1236 (microRNA 1236)
Synonyms: hsa-mir-1236; MIRN1236
Gene: MicroRNA gene on chromosome 6 (31,956,839 to 31,956,940, reverse strand). Ensembl gene ENSG00000284446.
Homologues: Orthologues: chimpanzee ptr-mir-1236 (100% identical).